RARRES2 (retinoic acid receptor responder 2)
Diseases named in the same sentence as RARRES2 in open-access papers (continued):
Sharing a sentence is not in itself a finding about the gene and the disease.
tumor (continued). "The expression of secreted protein‐coding genes, including MDK, HGF, RARRES2, GDF15, IL6 and MIA, was concentrated in the tumour cell‐enriched region, thus confirming the expression specificity of these signalling molecules." (PMID 38318640, 2024). "In order to track tumor cell behavior in vivo, we utilized BLI of luciferase-labeled RARRES2-OE 4T1 cells." (PMID 37491281, 2023). "In conclusion, a significant up-regulation of RARRES2 is identified in BE-GICs, and an increased proportion of TAMs and CD8 proliferative T cells is found in tumours with a larger fraction of astrocyte-like tumour cells." (PMID 36412091, 2022). "Results showed that the relative expression of LEF1, VLDLR, RARRES2 and TNFRSF10C were significantly up-regulated compared to adjacent non-tumor tissues and other metastatic sites (P < 0.05)." (PMID 34256750, 2021). "In addition to the tumor cells (dsRED+), we also found another cell cluster lacking the expression of dsRED that similarly express mesenchymal genes, but which was enriched for additional genes previously associated with CAFs, such as Rarres2, Pi16, Fap, Lum, Sfrp2, Dpt, and Col14a1 5,35." (PMID 38509063, 2024). "The interaction pairs via SPP1, RARRES2, NECTIN3, LGALS9, and LAMB1 showed increased signaling in the autophagy-high tumor cells, while SEMA3C, PTN, ICAM1, GAS6, and CSF1 showed decreased signaling compared with those in the autophagy-low tumor cells." (PMID 36830707, 2023). "Several studies have reported a tumor suppressive role of RARRES2 in cancer development, however, not much is currently known about the functions of RARRES2 in cancer cell lipid metabolism, and nothing is known regarding the association with RARRES2, lipid metabolism, and BCBrM." (PMID 37491281, 2023). "RARRES2 was found to be significantly up-regulated in BE-GICs compared to nBE-GICs, in both our cohort and the HGCC cohort, and in non-G-CIMP tumour tissue relative to non-tumour brain tissue." (PMID 36412091, 2022). "As a quality check of the enriched population, we assessed that the isolated cells lacked expression of tumor (dsRED), immune (Ptprc) and endothelial markers (Pecam1) and expressed the mouse CAF-specific signature we previously identified (e.g. Rarres2, Fap, Lum, Thy1)." (PMID 38509063, 2024).
cancer (17 papers, 2009 to 2026). A tumor composed of atypical neoplastic, often pleomorphic cells that invade other tissues. "Studies have shown that RARRES2 deficiency in cancer cells promotes TNBC brain metastasis by altering lipid metabolism in the brain microenvironment." (PMID 39402211, 2025). "This component features COL10A1, ITIH5, ADIPOQ, ADAMTS5, GPC3, SFRP1, and RARRES2 genes, pointing to their involvement in cancer-related cellular structures." (PMID 38253993, 2024). "We found that Rarres2 is upregulated in fibroblasts cultured in the presence of cancer CM, and its expression is further induced by co-culture with macrophages." (PMID 37726308, 2023). "Chemerin, a pleiotropic adipokine coded by the RARRES2 gene, has been reported to affect the pathophysiology of various cancer entities." (PMID 36900088, 2023). "In various cancers, RARRES2 can function as both a pro- and anti-inflammatory mediator, depending on the context." (PMID 37726308, 2023). "To gain insight into how RARRES2 affects TAMs, we monitored macrophage proliferation and migration in the presence of control medium, cancer CM, and cancer CM with recombinant RARRES2." (PMID 37726308, 2023). "Chemerin (also known as TIG-2 or RARRES2) is an adipokine and chemoattractant factor associated with obesity, inflammatory diseases and cancer." (PMID 29221117, 2017). "In addition, the chemerin (RARRES2 gene product)–CMKLR1 (chemokine-like receptor 1) axis has been reported to activate MSC migration to cancer tissue and damaged liver lesions." (PMID 35723360, 2022). "The correlation between RARRES2 and cancers has been reported." (PMID 34256750, 2021). "In some cases, cancers may silence RARRES2 via hypermethylation to evade immune surveillance." (PMID 30555465, 2018). "Importantly, for cases in which silencing of RARRES2 has been reported, the restoration and/or forced overexpression of chemerin in the microtumor environment may incite compelling antitumor effects, indicating new avenues of research for chemerin in cancer." (PMID 30555465, 2018). "This analysis confirmed that RARRES2 is secreted from CAFs and not from cancer cells." (PMID 37726308, 2023).
metabolic disorders (5 papers, 2018 to 2022). "Based upon our multiple analyses, we provided further and novel evidence about the important role of chemerin and RARRES2 variants involved in inflammation and metabolic diseases." (PMID 29720894, 2018).
infection (3 papers, 2021 to 2024). The state of being infected such as from the introduction of a foreign agent such as serum, vaccine, antigenic substance or organism. "Indeed, using in situ hybridisation on independent tissue sections, we were able to confirm the presence of Ly6a+ Rarres2+ cells that expressed Cxcl13+ during infection." (PMID 37983289, 2023). "In this study, we identified several proteins (FABP4, LEP, RARRES2, MSTN, C2, SELE and IL6) that belong to a family of chronic pro-inflammatory cytokines and are primarily produced in response to infection or stress, some of which are mainly produced by adipose tissue (FABP4, LEP and RARRES2)." (PMID 38548792, 2024).
heart disease (1 paper, 2017). "It would be of interest to study β-adrenergic and MEF2 regulation of Rarres2 in more detail in human heart disease." (PMID 28667250, 2017).
kidney disease (1 paper, 2025). "Renin, GDF15, PRSS8, RARRES2, PGLYRP1, LOX1, and UPAR, all robustly related to PA, have been related to cardiovascular or kidney disease via different pathways." (PMID 40498722, 2025).
RARRES2 also shares sentences with these, for which no sentence is quoted: diabetes (4 papers); cardiovascular diseases (3); coronary artery disease (2); endothelial dysfunction (2); gestational diabetes (2); metastatic melanoma (2); oral squamous cell carcinoma (2); acute myeloid leukemia (1); adenocarcinoma (1); anemia (1); aortic aneurysm (1); aortic valve stenosis (1); autoimmune disease (1); bacterial infection (1); Behcet’s syndrome (1); benign neurofibroma (1); bone tumor (1); brain tumors (1); chondrosarcoma (1); colorectal carcinoma (1); COVID-19 (1); focal epilepsy (1); glaucoma (1); heart failure (1); hematologic malignancies (1); invasive lobular carcinoma (1); kidney tumor (1); lupus erythematosus (1); metastatic tumors (1); myocardial infarction (1).
A further 8 diseases each share a sentence with RARRES2 in 1 paper.